LAG3 (lymphocyte activating 3)
Diseases named in the same sentence as LAG3 in open-access papers (continued):
Sharing a sentence is not in itself a finding about the gene and the disease.
autoimmune disease (continued). "Recently, HPS has been shown to be a functional ligand of the lymphocyte-activation gene 3 (LAG-3), inhibiting T-cell activation, and the ablation of HPS in aged mice causes autoimmune disease." (PMID 36362113, 2022). "While LAG-3 and PD-1 double knock-out (KO) mice exhibit an elevated autoimmune disease phenotype affecting multiple organs and leading to death, the majority of the same type of mice effectively cleared tumors and showed a significantly prolonged survival." (PMID 35693319, 2021). "Demonstration of LAG-3 function allows us to identify potential therapeutic approaches, both for autoimmune diseases (mimicking Treg functions) or malignancy (by inhibiting Treg functions)." (PMID 34907325, 2021). "The interaction of these genes (IL7R, CD40 and LAG3) with MHC class molecules is associated with MS and other autoimmune diseases." (PMID 32111053, 2020). "The immune-regulatory roles of LAG-3 were demonstrated in LAG-3 knockout mice, in which increased susceptibility to autoimmune diseases was observed." (PMID 30863404, 2019). "LAG3 plays a protective role in autoimmune diseases by dampening CD4+ T cell responses through MHC-II engagement and inhibiting effector T cell responses by promoting Treg and Tr1 suppression." (PMID 31434339, 2019). "Although LAG3 plays an important role in T cell inhibition in other diseases, such as cancer, autoimmune diseases, chronic viral infections, and parasites, its role in sepsis is not well-understood." (PMID 31440257, 2019). "Here, we described the first-in-class anti-LAG3 aptamer with potential therapeutic application for cancer immunotherapy or treatment of autoimmune diseases." (PMID 28934318, 2017). "Regulatory T cells (Tregs) play a role in the suppression of inflammation in autoimmune diseases, and lymphocyte activation gene 3 (LAG3) was reported as a marker of interleukin (IL)-10-producing Tregs." (PMID 28511719, 2017). "In cancer immunotherapy, antibodies that block the receptor on T cells have been developed, while depleting antibodies that target activated T cells that express LAG3 are used in clinical trials of autoimmune diseases." (PMID 28934318, 2017). "As the knockout of FoxP3, mice that lack LAG-3 exhibit leucocyte infiltrate in multiple organs followed by autoimmune disease." (PMID 26115356, 2015). "Adeeper understanding of LAG3+ Treg will be useful for the treatment ofautoantibody-mediated autoimmune diseases including SLE." (PMID 25695838, 2015). "Mice deficient in both LAG3 and PD1 proteins (Lag3−/−Pdcd1−/−) exhibit a wide range of severe autoimmune diseases that leads to 80% of lethality at 4–12 weeks after birth and enhanced antitumor activity in murine tumor models." (PMID 26318293, 2015). "Taken together, our observations indicate that LAG-3 has an important inhibitory role in the induction and maintenance of tolerance during the course of an induced experimental autoimmune disease." (PMID 25122007, 2014). "Notably, both HLA-I-specific and HLA-II-specific pGenes included known drug targets for autoimmune diseases, infectious diseases, and cancer such as LAG3, PDCD1, TNF, and ACE2 affected by HLA-I; and IL18, TREM2, VSIG4, and TLR1 by HLA-II." (PMID 39085222, 2024). "Co-inhibition of PD-1 and LAG-3 may cause fewer adverse events than co-inhibition of PD-1 and CTLA-4, which is characterized by single-deficient autoimmune disease." (PMID 37179337, 2023). "Unlike PD-1 and CTLA-4, LAG-3 single deficiency was not a factor of autoimmune disease without an autoimmune background and had less antitumor activity." (PMID 37179337, 2023). "LAG-3 induces autoimmune diseases and enhances antitumor activity by co-inhibiting PD-1." (PMID 37179337, 2023). "Considering the negative regulatory role of LAG3+ B cells in autoimmune diseases, we hypothesized that LAG3+ B cells were downregulated in RA patients." (PMID 37143367, 2023).
autoimmune disease (continued). "Numerous studies have confirmed the importance of LAG-3 in the pathogenesis of autoimmune diseases." (PMID 37915081, 2023). "Increasing evidence has elucidated that LAG-3 has remarkable cooperation with the quintessential inhibitory immune checkpoints PD-1/PD-L1, which can conjointly mediate immune homeostasis, abrogate autoimmune disease, and enhance tumor-induced tolerance." (PMID 30603054, 2018). "Nonetheless, in future applications, it could also be engineered for treatment of autoimmune diseases by target depletion of LAG3-effector T lymphocytes." (PMID 28934318, 2017). "Indeed, LAG-3 and PD-1 are commonly co-expressed on exhausted or dysfunctional T cells in models of chronic infections, autoimmune diseases, and cancers." (PMID 27415008, 2016). "The functional impairment of immune-regulatorymechanisms may be crucial for the initiation and perpetuation of autoimmune disease,and a reduced frequency of LAG3+ Treg in SLE could also play a role in thedysregulated autoantibody production." (PMID 25695838, 2015). "Our current studies demonstrate that mercury-induced autoimmune disease in LAG-3-deficient mice can be partially prevented by adoptive transfer of WT CD4+ T cells, thereby suggesting that LAG-3+ T cells are essential for maintenance of tolerance toward mercury." (PMID 25122007, 2014). "However, unlike CTLA-4 knockout mice, which show fatal autoimmune disease, LAG-3-deficient mice do not show signs of autoimmune disease." (PMID 38732104, 2024). "Although there is evidence on the role of LAG3 in other disorders, especially autoimmune diseases and cancer, the function of LAG3 in the CNS is largely unknown, and only recently, some experimental studies have begun to shed light on its role in neurodegenerative diseases." (PMID 32340360, 2020). "Thus further studies on LAG3+ Tregs could provide insights into the development of new therapeutic targets for autoimmune diseases." (PMID 29535721, 2018). "Lymphocyte activation gene-3 (LAG-3) is a type I transmembrane protein structurally similar to CD4 and functions as an inhibitory co-receptor critical in autoimmune diseases, tumor immunity, and anti-infective immunity." (PMID 39911397, 2025). "Lymphocyte activation gene 3 (LAG-3), an inhibitory protein discovered in 1990, is expressed in T cells, B cells, NK cells, dendritic cells and TILs, and plays a role in autoimmune diseases, chronic infections and cancer." (PMID 36945923, 2023). "Tr1 cells originate extra-thymically, lack FoxP3 but express CD49b and lymphocyte activation gene 3 (LAG-3), produce IL-10 and TGF-β thereby maintaining immune homeostasis and preventing autoimmune diseases." (PMID 37346034, 2023). "It should be noted that despite the observed shifts toward activated immune cell phenotypes, unmanipulated LAG3–/– mice did not exhibit signs of autoimmune disease up to 6 months of age." (PMID 40359031, 2025). "Though mice lacking LAG-3 do not develop spontaneous autoimmune disease in non-autoimmune prone mouse strains, LAG-3 induced lethal myocarditis in BALB/c mice deficient for the gene encoding for PD-1." (PMID 35784333, 2022). "Finally, we assess the possibility of developing mAbs that enhance, rather than block, LAG3 inhibitory activity as treatments for autoimmune diseases." (PMID 38556085, 2024). "In addition, no patient was treated with the FDA and EMA approved LAG-3 immune checkpoint inhibitor relatlimab and the data on the safety of this immune checkpoint for patients with autoimmune diseases is missing." (PMID 38268921, 2023).
hepatocellular carcinoma (47 papers, 2018 to 2026). A malignant tumor that arises from hepatocytes. "We evaluated the effect of PDCD-1 and LAG3 gene polymorphisms on the risk of hepatocellular carcinoma (HCC) in this study." (PMID 37131179, 2023). "This study evaluated the effects of PDCD-1 (rs10204525 and rs36084323), and LAG3 (rs870849 and rs1882545) gene polymorphisms on hepatocellular carcinoma (HCC) risk." (PMID 37131179, 2023). "Similar tendencies were observed in immunotherapy-treated hepatocellular carcinoma, where high LAG-3 expression was associated with shorter progression-free survival." (PMID 36077354, 2022). "In hepatocellular carcinoma (HCC), higher densities of LAG-3+cells were associated with shorter OS and disease-free survival (DFS)." (PMID 35669786, 2022). "In hepatocellular carcinoma (HCC) elevated densities of LAG-3+cells and low levels of CD8+ T cells are associated with poor disease outcomes and shorter overall survival." (PMID 36077354, 2022). "SATB1 overexpression not only reduced expression of multiple inhibitory receptors (PD-1, CTLA-4, TIM3, and LAG-3) but also promoted a central memory phenotype, enhancing cytokine production and cytotoxicity against hepatocellular carcinoma (HCC) cells in vitro." (PMID 41372119, 2025). "Increased LAG3 expression in tumor-infiltrating lymphocytes (TILs) has been reported in hepatocellular carcinoma, and blockade of the binding of LAG3 to its ligand, MHC-II, leads to an increase in the number of TILs and enhances their ability to secrete cytokines, thus promoting anti-tumor immunity." (PMID 40298450, 2025). "Hsu and colleagues found that exhausted CD8+LAG3+ T cells could predict efficacy of single-agent immunotherapy versus immunotherapy combination therapies in hepatocellular carcinoma." (PMID 35892867, 2022). "Based on the in vitro and in vivo results, we hypothesized that Oxysophocarpine could suppress the hepatocellular carcinoma growth and sensitize the therapeutic blockade of anti‐Lag‐3." (PMID 32810392, 2020). "Immune checkpoints PD‐1, TIM‐3, and LAG‐3 were also shown to be upregulated in TILs of hepatocellular carcinomas and may enhance T‐cell response to tumor antigens in a synergistic way." (PMID 32506804, 2020). "The potential of immunotherapy is yet unfolding, with novel immune targets such as LAG3 or VISTA being evaluated, and CAR-T cell therapy showing the first promising results in gastric and hepatocellular carcinomas." (PMID 39809756, 2025). "The most significant immune biomarkers for hepatocellular carcinoma were employed in immunotherapy, according to earlier research: PDCD1, CTLA4, HAVCR2/TIM3, and LAG3." (PMID 38248311, 2023). "In hepatocellular carcinoma (HCC) tissues, the expression of PD-1, TIM-3 and LAG-3 was increased on T-cells." (PMID 34575943, 2021). "Interestingly, in this respect, high Siglec-10 levels in hepatocellular cancer patients correlated with significantly higher expression of inhibitory receptor genes such as PD1, TIM3, CTLA-4, or LAG-3 in a more recent study." (PMID 35625912, 2022). "LAG-3 and T-cell immunoglobulin and mucin structural domain molecule-3 (Tim-3), are also upregulated on specific CD8+ T cells in various cancer types and are also involved in the progression of hepatocellular carcinoma." (PMID 34869039, 2021). "Recently, LAG3 expression was previously found to be significantly higher in CD8+ tumor-infiltrating helper T cells and CD8+ cytotoxic T cells than in tumor-free liver tissue and blood from patients with hepatocellular carcinoma." (PMID 34869039, 2021). "CD8+ TILs isolated from tumors such as hepatocellular carcinoma (HCC), melanoma, ovarian cancer, and microsatellite instability high (MSI) colorectal cancer (CRC), have high levels of both PD-1 and LAG-3." (PMID 34025438, 2021).
hepatocellular carcinoma (continued). "For chimeric antigen receptor T-cell (CAR-T) therapy, hepatocellular carcinoma (HCC) organoid models revealed enhanced cytotoxicity of CD39+ CAR-T cells targeting hepatitis B virus (HBV) antigens, which was further potentiated by PD-1/Tim-3/Lag-3 knockdown." (PMID 41155654, 2025).
lymphoma (46 papers, 2015 to 2025). A malignant (clonal) proliferation of B- lymphocytes or T- lymphocytes which involves the lymph nodes, bone marrow and/or extranodal sites. "Here we analyzed a cohort of 112 lymphoma patients treated with CAR-T cell therapy according to their germline LAG3 gene variants (LAG3 I455hom, I455Thet, T455hom)." (PMID 41155207, 2025). "An increased proportion of LAG3+ lymphoma cells PD-L2+, PD-1+, PD-L1+ is the predominate cause of immune escape of diffuse large B cell lymphomas." (PMID 38025757, 2023). "Serum levels of IL-12 are elevated in lymphoma patients and are associated with T-cell exhaustion and we wondered whether IL-12 played a role in the regulation of LAG-3 expression on T cells." (PMID 28977875, 2017). "Now we present evidence of favorable clinical outcome to CAR-T cell therapy in lymphoma patients of the same cohort carrying a germline LAG3 rs870849." (PMID 41155207, 2025). "We previously analyzed the clinical impact of CTLA4 rs231775 in the same lymphoma cohort which prompted a stratified analysis in all genetic combinations of LAG3 rs870849 and CTLA4 rs231775 in the current study." (PMID 41155207, 2025). "The sequence of the LAG3 gene exon seven was determined in the peripheral blood cells of 112 lymphoma patients evaluated for CAR T-cell therapy at our center." (PMID 41155207, 2025). "Other T cell checkpoints (LAG-3, TIM-3, TIGIT) have been associated with lymphoma progression but clinical data on therapeutic targeting of these checkpoints are not available yet." (PMID 38322418, 2024). "Many clinical trials of anti-LAG3 mAbs are underway for treating multiple solid tumors and lymphomas." (PMID 38556085, 2024). "LAG-3 inhibition in combination with PD-1 axis blockade is being studied in R/R lymphomas in an effort to overcome resistance to PD-1 directed monotherapy and results are awaited (NCT02061761)." (PMID 38322418, 2024). "As a result, nearly 20 anti-LAG3 mAbs are currently in clinical trials for immunotherapy of multiple solid tumors and lymphomas." (PMID 38556085, 2024). "Although there are few clinical trial results for anti‐LAG‐3 antibodies in lymphoma, several studies have experimentally shown the potential of LAG‐3 as a target for DLBCL treatment." (PMID 37326144, 2023). "Currently active trials include NCT03489369, a Phase I, open-label trial assessing safety, tolerability, and antineoplastic activity of an Anti-LAG-3 mAb (Sym022) in advanced solid tumors and lymphomas." (PMID 37920162, 2023). "Although there are not currently enough data to demonstrate the value of LAG3+ T cells as a predictor of unfavorable responses, ongoing lymphoma clinical trials are targeting LAG3, including in cHL patients." (PMID 35267668, 2022). "Two bands were observed using rabbit SP464 in the human lymphoma cell lines, one corresponding to soluble endogenous LAG3 (52 kDa) and a second higher intensity band corresponding to full length endogenous LAG3 (58 kDa)." (PMID 36278613, 2022). "Sym022 (anti-LAG-3) was evaluated as a single agent or in combination with sym021 (anti-PD-1) in phase 1 trials for solid tumors or lymphomas (NCT03311412, NCT03489369, and NCT03489343)." (PMID 34025438, 2021). "In this review, we describe the TME of common lymphoma subtypes with an emphasis on the role of prominent immune checkpoint molecules PD-1 and LAG3." (PMID 34068762, 2021). "With regards to lymphoma, the small number of studies performed to date indicate the likely important contribution of LAG-3 to immune suppression within the TME and early evidence points to particular importance in cHL and PMBCL." (PMID 34068762, 2021). "Several anti-LAG3 antibodies have being developed and some of them are in early-phase clinical trials for R/R lymphomas (NCT03489369, NCT03005782, NCT02061761)." (PMID 33327433, 2020).
lymphoma (continued). "To determine the specific cellular distribution of ICP expression in lymphoma samples, we evaluated the staining of PD-1, PD-L1, LAG-3, and TIM-3 in the ME and in tumor cells with a cutoff value of 10% for ME cells and 20% for tumor cells." (PMID 30384489, 2018). "Given that lymphoma-associated LAG-3+ T cells were functionally exhausted, we predicted that intratumoral LAG-3+ T cells would adversely affect patient outcomes in FL." (PMID 28977875, 2017). "In summary, we present data in the present study showing that LAG-3 expression in lymphoma tissue specifically identifies the cells within the PD-1+ T cell population that are functionally exhausted." (PMID 28977875, 2017). "Lymphocyte-activation gene-3 (LAG-3) is another immune checkpoint which is currently being targeted in a phase 1 study in hematologic malignancies, including lymphoma (NCT02061761)." (PMID 26393619, 2015). "Indeed, nearly 20 anti-LAG3 mAbs or LAG3 bispecifics are now in over 100 clinical trials for treating multiple solid tumors and lymphomas." (PMID 38556085, 2024). "HLX26 is another anti-LAG-3 mAb being investigated in solid tumors and lymphomas in NCT05078593." (PMID 37920162, 2023). "We will also discuss current clinical evidence for ICB in lymphoma and highlight key areas for further investigation where synergistic dual checkpoint blockade of LAG-3 and PD-1 could be used to overcome ICB resistance." (PMID 34068762, 2021). "There is still limited single agent data for the use of anti-LAG-3 based therapy in lymphoma." (PMID 34068762, 2021). "Another anti-TIM-3 antibody (Sym023) is currently being tested in phase I clinical trials in patients with lymphoma refractory to currently available therapies, in monotherapy or in combination with anti-PD-1 (Sym021) or anti-LAG-3 (Sym022) antibodies (NCT03489343 and NCT03311412)." (PMID 31867006, 2019). "Lymphocyte activation gene-3 (LAG-3) is a cell surface immunomodulatory receptor commonly co-expressed with PD-1 on exhausted T cells and may serve as an escape pathway for lymphoma subjected to PD-1 blockade." (PMID 30400835, 2018). "Rather, dual blockade of both PD-1 and LAG-3 may specifically target the exhausted T-cell population and may therefore be a promising future treatment approach in lymphoma patients." (PMID 28977875, 2017). "We next explored whether LAG-3 was co-expressed with TIM-3 in intratumoral T cells in lymphoma." (PMID 28977875, 2017). "However, LAG-3 was highly expressed on CD4+ or CD8+ T cells from lymphoma biopsies." (PMID 28977875, 2017). "This study focused solely on the expression of CXCR5 and LAG‐3 in peripheral blood CD8+ T cells, as we were unable to obtain lymphoma and normal lymphoid tissue samples." (PMID 40091778, 2025). "Downregulated genes in the absence of EBV in children included genes associated with key immune regulators (IL-10) and immune checkpoint genes (LAG3 and CD274), suggesting the impact of EBV infection in the modulation of immune response in pediatric lymphomas." (PMID 40461625, 2025). "Currently, clinical trials evaluating the safety and efficacy profiles of anti-LAG-3 and anti-TIM-3 therapy in combination with PD-1 blockade in lymphoma is ongoing, such as NCT03311412 and NCT02061761, and results are eagerly awaited." (PMID 36959853, 2023). "The same investigators are further assessing Anti-PD-1 therapy in combination with either Anti-LAG-3 or Anti-TIM-3 in both advanced solid tumors and lymphomas (NCT03311412)." (PMID 37920162, 2023). "In summary, here, we show that, in spite of the similar anti-lymphoma activity, AWARI CAR-T cells exhibit a milder secretion of TNF-α and IFN-ɣ as well as reduction in LAG-3 expression, both important players in CRS." (PMID 35694446, 2022). "Sym021 (anti-PD-1), sym022 (anti-LAG-3), and sym023 (anti-TIM-3) were evaluated as single agents or combinations in phase 1 trials for solid tumors or lymphomas (NCT03311412, NCT03489369, and NCT03489343)." (PMID 34025438, 2021).